INS (insulin)
Diseases named in the same sentence as INS in open-access papers (continued):
Sharing a sentence is not in itself a finding about the gene and the disease.
Hyperglycemia (continued). "Such is the case of hyperglycaemia‐evoked insulin surge and the subsequent rise in plasma leptin that acts on the transient receptor potential melastatin 7 channels of CB glomus cells to raise sympathetic activity and blood pressure." (PMID 36999224, 2023). "An inability to match insulin delivery with an individual’s changing insulin requirements results in either hypoglycemia (low blood glucose level) or hyperglycemia (high blood glucose level)." (PMID 35200143, 2022). "While the microvascular complications start to develop with the onset of hyperglycemia, the macrovascular complications develop at the onset of insulin resistance." (PMID 36326311, 2022). "The incidence of hyperglycemia in the current study was similarly 12.2% (6/49 patients) and only one-third of all patients received insulin care as a predetermined protocol." (PMID 36266449, 2022). "Dual GIP and GLP-1 receptor co-activation enhances insulin secretion by 20–30% more than the single administration, improves insulin sensitivity, and reduces glucagon secretion, and the reduction in hyperglycemia additionally reduces the resistance to GIP." (PMID 36289848, 2022). "Modest data on the effects of central GLP-1R inhibition indicate that during hyperglycemia, such a treatment leads to increased peripheral glucose utilization and insulin sensitization in mice." (PMID 35008973, 2022). "The increase in fasting glucose is characterized by increased hepatic glucose production and reduced early insulin secretion, while postprandial hyperglycemia is mainly due to peripheral insulin resistance." (PMID 36012115, 2022). "The aim of control strategies for artificial pancreas systems is to calculate the insulin doses required by a subject with type 1 diabetes to regulate blood glucose levels by reducing hyperglycemia and avoiding the induction of hypoglycemia." (PMID 35265035, 2022). "Similar findings have shown that apocynin significantly reduced hyperglycemia, hyperinsulinemia, and dyslipidemia by improving insulin sensitivity in high-fat-diet (HFD)-induced obese mice as well." (PMID 35629342, 2022). "Hnf1a-null mice showed impaired insulin secretion and subsequent hyperglycemia, suggesting that HNF1A was involved in insulin secretion in mouse beta cells." (PMID 35328643, 2022). "To test the effects of insulin treatment on hyperglycemia-induced depressive behaviors, we performed the first FUST 3 weeks after the STZ injection." (PMID 36552776, 2022). "Impaired hepatic insulin sensitivity induces to increased hepatic gluconeogenesis, hyperinsulinemia, β-cell hypertrophy, and hyperglycemia." (PMID 36547081, 2022). "The results showed that insulin stimulation of HEC-1A cells at first causes the increase and then decrease in BMI-1 expression both in hypoglycemia and hyperglycemia conditions." (PMID 36497428, 2022). "Mice that were treated with either DAPA or insulin showed a marked reduction in hyperglycemia and HbA1c." (PMID 35281932, 2022). "Accordingly, injection of purified human α-subunit increases blood glucose levels in mice, and transgenic mice secreting soluble α-subunit into the plasma have chronic hyperglycaemia, presumably due to sequestering of plasma insulin after binding to the sIR." (PMID 35742925, 2022). "GDM is a state of hyperglycaemia that occurs when a woman’s endogenous insulin production is unable to compensate for the hormonal changes that occur in pregnancy, making her more insulin resistant." (PMID 36584120, 2022). "As a consequence, β-cells are destroyed and unable to secrete insulin which results in the development of DM hyperglycemia." (PMID 35815262, 2022). "In type 2 diabetes, pancreatic β-cells fail to release enough insulin to compensate for hyperglycemia." (PMID 35276982, 2022).
Hyperglycemia (continued). "Agonists of gut-derived glucagon-like peptide-1 (GLP-1), gastrointestinal hormones able to increase insulin secretion in response to hyperglycaemia (incretins), have been recently introduced in T2DM therapy, quickly entering the international guidelines." (PMID 36077515, 2022). "Although increased fasting GCGN levels cause hyperglycemia GCGN has beneficial actions by stimulating hepatic lipolysis and improving insulin sensitivity through alanine induced activation of AMPK." (PMID 35662921, 2022). "As a result, the inhibition of alpha-glucosidase activity can result in a substantial delay in post-prandial hyperglycemia and a favorable impact on insulin resistance and glycemic index regulation." (PMID 36204125, 2022). "Sodium–glucose cotransporter 2 (SGLT2) inhibitors, a new class of oral hypoglycemic agents, ameliorate hyperglycemia by inhibiting glucose reabsorption in the proximal tubule of the kidney, thereby functioning in an insulin-independent manner." (PMID 36686683, 2022). "Mandatory glucose absorption has been shown to be associated with several unfavorable metabolic complications, such as hyperglycemia, increased insulin need, weight gain and increased visceral fat, dyslipidemia, and metabolic syndrome." (PMID 36079811, 2022). "For exercises that last longer than one hour, small boluses of short-acting insulin given during exercise are necessary to prevent hyperglycemia." (PMID 35345701, 2022). "All currently US Food and Drug Administration (FDA)-approved insulin still have a narrow therapeutic window: insulin overdoses lead to hypoglycemia and underdoses result in hyperglycemia." (PMID 35372263, 2022). "DM is one of the most prevalent metabolic disorders resulting from chronic hyperglycaemia due to problems in insulin secretion, insulin action or both." (PMID 36438767, 2022). "Early studies mainly focused on producing pure β-cells, which ideally have the capacity to secrete sufficient insulin stimulated by glucose and ameliorate hyperglycemia." (PMID 35966093, 2022). "DM is a metabolic disease of defective insulin secretion in response to glucose and impaired insulin sensitivity defined by hyperglycaemia and, similar to frailty, results from the complex interplay of genetic and acquired factors." (PMID 36992729, 2022). "As many of these tissues’ cells, e.g., ocular cells, are insulin independent, the response to hyperglycemia-induced signaling is complex and tissue specific." (PMID 36290725, 2022). "In hyperglycemia, more insulin secretion is related to pancreatic vacuolation with concomitant use of quinolones." (PMID 35203750, 2022). "In the prevention of hyperglycaemia, information about the height and timing of the postprandial glucose peak in diabetic patients who depend on exogenous insulin to reduce postprandial glycaemia is important." (PMID 36011551, 2022). "Insulin implants at the time of initial hyperglycemia were protective against low tear production in female rats, but not in male rats, as the T1D-INS male animals had significantly reduced tear volumes beginning 6 weeks after hyperglycemia was measured." (PMID 36274979, 2022). "The hormone insulin is secreted by the pancreas when blood glucose levels increase above normal values, i.e., hyperglycemia, to promote glucose uptake in the liver and skeletal muscle." (PMID 36557261, 2022). "For example, taurine improves hyperglycemia in diabetic model animals by modifying glucagon activity, insulin sensitivity, and insulin secretion." (PMID 35163722, 2022). "Oxidative stress leads to impairment of insulin secretion in β-cells and IR progress in adipocytes and peripheral tissues that eventually accelerates postprandial hyperglycemia and overt T2DM." (PMID 35711333, 2022). "This hyperglycaemia arises from an inability of the insulin-sensitive cells to sufficiently respond to the secreted insulin, which eventually results in the inadequate secretion of insulin from pancreatic β-cells." (PMID 35053127, 2022).
Hyperglycemia (continued). "Insulin-resistant adipose tissue displays impaired glucose and triglyceride uptake under insulin stimulation, leading to hyperglycemia and hyperlipidemia." (PMID 36555704, 2022). "Hyperglycemia results from a mismatch between the insulin secretion from the pancreatic β-cells and the ability of tissues to take up glucose in response to insulin." (PMID 35215537, 2022). "Regarding glucose homeostasis, severe SARS-CoV-2 infection contributes to insulin resistance and hyperglycemia by increased cytokines and unregulated compensatory hormonal response." (PMID 36140191, 2022). "Obesity-related hyperglycemia can be largely attributed to the increased hepatic gluconeogenesis, which is mainly controlled by insulin signaling." (PMID 36547931, 2022). "None of the hyperglycemia trends and antidiabetic treatments reviewed in the present study, i.e., persistent hyperglycemia, severe hyperglycemia, or insulin prescription, were independent predictors of 42-day mortality." (PMID 36675866, 2022). "Treatment with IL1 receptor antagonists has been shown to decrease hyperglycemia, enhance B cell function and increase insulin sensitivity in peripheral tissues, notably the liver." (PMID 36160451, 2022). "PI3-K is involved in the IRS substrate pathway, which is impaired by insulin inefficiency and hyperglycemia." (PMID 36248900, 2022). "GLP-1 protects against hyperglycemia mainly by two mechanisms: enhancement of insulin secretion in beta-cells and inhibition of glucagon secretion in alpha-cells." (PMID 35933633, 2022). "In our study, after eight weeks on the HFD, the body weight of mice steadily increased followed by hyperglycemia, hyperlipidemia, and impaired glucose and insulin tolerance, which is in accordance with the previous in-vivo studies." (PMID 35928902, 2022). "In turn, this hyperglycaemia leads to reduced insulin sensitivity and increasing insulin secretion, interfering with glucagon-like peptide 1 (GLP-1) and enhances the production of glucagon." (PMID 36293857, 2022). "Participants also stated that individuals should not fast if they are physically incapable of fasting, experiencing severe physical symptoms, suffering from hypo- or hyperglycaemia, using insulin or in a life-threatening situation." (PMID 35245315, 2022). "The rate of gastric emptying is a major determinant of the glycemic/insulin responses following a meal and has been shown to correlate positively with postprandial hyperglycemia." (PMID 35215472, 2022). "Outcome variables: fasting and post-challenge insulin sensitivity and secretion indices, corresponding disposition indices (DI), plasma glucose at fasting and 1 and 2 h, hyperglycemia in pregnancy (HiP)." (PMID 36014761, 2022). "Type 1 diabetes (T1D) arises from autoimmune-mediated destruction of insulin-producing β-cells leading to impaired insulin secretion and hyperglycemia." (PMID 35155683, 2022). "On the other hand, long-acting GLP-1 agonists have shown substantial decreases in fasting blood glucose levels and modest reductions of postprandial hyperglycemia with strong stimulations of fasting insulin secretions and reductions of glucagon secretion." (PMID 35054924, 2022). "Taken together, the GvAEx treatment had attenuated hyperglycemia and improved glucose tolerance and insulin sensitivity in db/db mice." (PMID 35721172, 2022). "Patients with Type-1 diabetes (T1D) resulting from autoimmune destruction of β-cells exhibit hyperglycaemia due to low levels of blood insulin." (PMID 36140793, 2022). "Among treated participants, 865 (80.1%) received oral hypoglycemic agents, 97 (9.0%) received insulin, and 118 (10.9%) received both oral agents and insulin for the treatment of hyperglycemia." (PMID 36253738, 2022). "Hyperinsulinemia, hyperglycemia, dyslipidemia, HTN, and a pro-inflammatory state are all associated with IR, as are the consequences of disrupted insulin signaling at the endothelial cell level (endothelial cells and vascular smooth muscle cells)." (PMID 35370984, 2022).
Hyperglycemia (continued). "Inflammation in the liver has been reported to impair insulin signaling, resulting in an inability to suppress glucose production and ultimately leading to hyperglycemia." (PMID 36387912, 2022). "This apparent sex difference was likely due to the exclusive use of basal insulin in the male patients, which provided a low level of exogenous insulin during the study assessments thereby mitigating the effects of hyperglycaemia on QTc." (PMID 35596784, 2022). "In diabetic mice, it was also found that dietary COS reduced hyperglycemia by activating hepatic glucokinase and increasing peripheral tissue glucose uptake, as well as by increasing pancreatic insulin secretion and improving skeletal muscle glucose uptake." (PMID 36080631, 2022). "A total of 121 subjects with HIP requiring insulin therapy were enrolled from a prospective cohort consisted of 436 pregnant women with hyperglycemia." (PMID 36339424, 2022). "The inhibition of 11β-HSD1 ameliorated hyperglycemia and improved insulin sensitivity in diabetic mice." (PMID 36232291, 2022). "Known factors contributing to hyperglycaemia include reduced insulin secretion, decreased glucose utilization, and increased glucose production, and several medicine, like antihypertensive drugs and protease inhibitors." (PMID 36424607, 2022). "Because insulin is the only hormone that reduces the blood glucose concentration, if the secretion of insulin is insufficient, chronic hyperglycemia results." (PMID 35563495, 2022). "On the other hand, MDI with rapid-acting insulin is given to meet the meal insulin needs and refine the hyperglycemia condition." (PMID 36411933, 2022). "In prediabetes and the early stages of T2D, impaired glucose tolerance, or hyperglycemia, is accompanied by compensatory hyperinsulinemia due to decreasing insulin sensitivity." (PMID 36497026, 2022). "DM, one of the fastest growing chronic diseases in the USA, the EU, and other countries, is a metabolic disease characterized by hyperglycemia due to defects in insulin secretion, insulin action, or both, leading to hyperglycemia." (PMID 35270009, 2022). "DM is characterized by hyperglycemia resulting from inadequate insulin production, and/or impaired insulin action." (PMID 35473620, 2022). "Type 2 diabetes (T2D), formerly called non-insulin-dependent diabetes) is a category of metabolic disorders distinguished through hyperglycemia, resulting in abnormalities in insulin production or insulin function." (PMID 36553074, 2022). "Critically, we observed that the pharmacological agent C29 (ERRα inverse agonist) ameliorated the HFD-induced NAFLD in the ERRα3SA mice concomitantly with the reversal of dyslipidemia and hyperglycemia, thereby increasing insulin responsiveness." (PMID 35440636, 2022). "It encompasses a group of chronic disorders characterized by hyperglycemia, resulting from pancreatic islet dysfunction or as a consequence of insulin-producing β-cell death." (PMID 39872972, 2022). "It is characterized by chronic hyperglycemia and other abnormalities including defect in insulin secretion, resistance to insulin in liver, skeletal muscles, and adipose tissues, and exaggerated hepatic glucose production." (PMID 35388310, 2022). "Induction and re-induction were complicated by steroid-induced hyperglycemia that required multiple-week insulin." (PMID 35399095, 2022). "Of interest, adipsin levels are reduced in T2D patients with β-cell failure, while exogenous administration of adipsin to diabetic mice reduced hyperglycemia by boosting insulin secretion." (PMID 35628332, 2022). "The main mechanisms leading to hyperglycaemia are increased insulin resistance and glucose production via hepatic gluconeogenesis, and inhibition of insulin production and secretion by pancreatic ß-cells." (PMID 35256883, 2022).
Hyperglycemia (continued). "Rich in essential amino acids (EAAs), non-essential amino acids (NEAAs) and essential branch-chain amino acids (BCAAs), whey protein isolate (WPI) can decrease postprandial hyperglycemia and promote insulin secretion in both healthy and diabetic individuals." (PMID 36992769, 2022). "Hyperglycemia > 8 mmol/L (>145 mg/dL) should be avoided, and it is recommended to treat repetitive blood glucose levels > 10 mmol/L (>180 mg/dL) with continuous insulin infusion." (PMID 35565787, 2022). "More importantly, a targeted delivery of mPEG-PCL-g-PDMAEMA nanoparticles/miR-190 complexes (PECgD NPs/miR-190) to the pancreas significantly ameliorated hyperglycemia, decreased fasting serum insulin levels, and improved glucose tolerance in diabetic mice." (PMID 35971429, 2022). "Alloxan-induced hyperglycemia was observed to be considerably lower in AG-treated diabetic rabbits; serum insulin level was found to be significantly restored." (PMID 34986201, 2022). "Some AYAs, particularly females, deliberately omitted insulin doses to induce hyperglycemia for inpatient admission to avoid school exams or family conflicts (Quote #3)." (PMID 38515508, 2022). "Metformin has good safety in the treatment of hyperglycemia and can enhance insulin sensitivity at the same time." (PMID 35813613, 2022). "Suppression of the deterioration of β-cell through these mechanisms halts reduced insulin secretion, thereby avoiding the state of hyperglycemia." (PMID 35282429, 2022). "In our study, hyperglycemia-induced insulin secretion increased progesterone secretion and progressive autonomic imbalance." (PMID 35743808, 2022). "T2DM represents the disturbance of the metabolomic homeostasis via a low insulin:glucagon ratio, with decreased insulin and increased glucagon production pushing the balance toward hyperglycemia." (PMID 36013384, 2022). "In our study, the results of OGTT and ITT showed intolerance of glucose and decreased insulin sensitivity in MBCDs-treated mice, indicating the primary mechanism of MBCDs-induced hyperglycemia was IR." (PMID 35842638, 2022). "Namely, it is well-known that fetal hyperinsulinemia is the main driver of fetal overgrowth, whereas, for fetal insulin secretion was shown that it is possibly suppressed by chronic hyperglycemia and stimulated by short glucose fluctuations." (PMID 36140278, 2022). "For example, insulin-independent hyperglycemia increases the size of liver tumors and reduces apoptosis in a tumor-prone animal model, whereas in T1D in vivo models tumor growth is reduced by insulin." (PMID 36531496, 2022). "Under HFD-fed conditions, hepatic gluconeogenesis is activated, resulting in hyperglycemia and high insulin levels stimulating liver fatty acid synthesis from glucose and TG formation." (PMID 36099304, 2022). "Further workup (Glycated hemoglobin, C-peptide, diabetes related autoantibodies) excluded the possibility of type 1 diabetes, and hyperglycemia had resolved after 31 days of insulin therapy." (PMID 35399095, 2022). "Considering the long duration of action of this novel insulin construct, it would likely function as a basal insulin, leading to post prandial hyperglycemia." (PMID 35621084, 2022). "Experience from Severe Acute Respiratory Syndrome (SARS) and Middle East Respiratory Syndrome (MERS) suggests that inflammatory cells can affect the liver, impairing insulin-mediated glucose uptake, with hyperinsulinemia and hyperglycemia as a result." (PMID 35250853, 2022). "Maternal hyperglycemia and subsequent fetal hyperglycemia lead to hyperactivation of the pancreas with excessive insulin production." (PMID 36143839, 2022). "We have ventured to point out that the fetal beta-cells start secreting insulin at 10-11 weeks of pregnancy and fetal hyperinsulinemia persists with maternal hyperglycemia, in a pregnant woman who would develop gestational diabetes." (PMID 36540507, 2022).